ENSG00000260914 (novel protein)
Gene: Protein-coding gene on chromosome 16 (69,299,682 to 69,322,700, forward strand). Ensembl gene ENSG00000260914.
Genetic constraint (gnomAD): Loss-of-function variants: 21 observed, 49.94 expected, observed/expected ratio (o/e) 0.42, 90% interval 0.3 to 0.61. The synonymous counts are far from expectation, so gnomAD's model fits this gene poorly and the ratio says little. Missense variants: 404 observed, 555.13 expected, observed/expected ratio (o/e) 0.73, 90% interval 0.67 to 0.79. Synonymous variants: 282 observed, 221.03 expected, observed/expected ratio (o/e) 1.28, 90% interval 1.16 to 1.41.